CD4 (CD4 molecule)
Diseases named in the same sentence as CD4 in open-access papers (continued):
Sharing a sentence is not in itself a finding about the gene and the disease.
tumor (continued). "To further explore the underlying mechanisms, we evaluated treatment effects on tumor-infiltrating lymphocytes (TILs), including CD4-CD8+ T cells, CD4+CD8- T cells, CD4-CD8+GZMB+ T cells (activated CD8+ T cells) and CD4+CD8-CD25+FXOP3+ (Tregs)." (PMID 41522360, 2026). "Key markers included C-reactive protein, albumin, neutrophil and lymphocyte counts, creatinine, bilirubin, international normalized ratio, tumor size and number, alpha-fetoprotein, platelet count, and CD4+/CD8+ T-cell levels." (PMID 41869666, 2026). "CD4 + Th1-mediated functions are essential for effective anti-tumor responses, as they promote the proliferation and cytotoxic activity of CD8 + CTLs and NK cells." (PMID 41582199, 2026). "This combinatorial strategy also reshaped the tumor immune landscape by increasing activated NK cells, elevating Granzyme B expression in CD4+ T cells, and decreasing immunosuppressive M-MDSCs expressing CD39, CD38, and CD73." (PMID 41668741, 2026). "Compared with their counterparts in normal lung tissue, tumor-infiltrating CD4+ TRMs exhibited elevated expression of immune checkpoint molecules, indicating a dysfunctional state, accompanied by significantly reduced XCL1 expression." (PMID 41486351, 2026). "Compared with the BM counterparts, we found these tumors to have a significantly reduced effector-to-tumor cell ratio, a significantly lower number of CD4+ T cells, and an increased proportion of regulatory CD16- NK cells." (PMID 41236394, 2026). "Single-cell transcriptomic studies have further identified tumor-associated atypical B cells marked by FCRL4 expression, enriched for MHC-II and CD4+ T-cell interactions, and precursors of antibody-secreting cells." (PMID 41364090, 2026). "After 48 h of direct co‐culture, DDKC tumor cells displayed a greater potential to differentiate activated CD4+ T cells into CD4+FoxP3+ Tregs than KC cells." (PMID 41147409, 2026). "Increased IFN-β secretion inhibits NSCLC cell proliferation and increases the infiltration levels of CD4+ T cells, M1 macrophages and NK cells into the tumor microenvironment, consequently inhibiting NSCLC progression." (PMID 41545343, 2026). "MHC II molecules are crucial for antigen presentation of tumor-derived antigens to CD4+ ​​​​​T-cells, which are key to orchestrating broader adaptive antitumor immune responses." (PMID 41431358, 2026). "Functionally, SATB1 KO reduces human Treg cell suppressive capacities but boosts tumor clearance via CD4 CAR T cells in a preclinical, humanized mouse model." (PMID 42051317, 2026). "In contrast, cluster 16 (CD4+ T cells PD1+) was significantly increased upon combination treatment of the IUE-24-C5 tumor bearing mice." (PMID 41541220, 2026). "Beyond this quantitative loss, our data further revealed that HBV compromises the anti‐tumour capacity of CD4+ T cells, thereby imposing an additional layer of immune suppression that aggravates immune evasion and accelerates disease progression." (PMID 41492119, 2026). "In the control group, CD4+ T cells were concentrated within the tumor center, whereas in the fatty liver group, they were marginalized toward the tumor edge." (PMID 41545340, 2026). "Tumor-infiltrating CD4+ TRMs exert helper antitumor effects by secreting the chemokine XCL1 to recruit conventional type 1 dendritic cells (cDC1s), facilitating antigen presentation and priming cytotoxic T lymphocyte responses." (PMID 41486351, 2026). "Therapeutic restoration of miR‐19a‐3p or blockade of TGF‐β reinforced the CD4+ T cell anti‐tumour activity and restrained the progression of HBx‐overexpressing DLBCL in vivo." (PMID 41492119, 2026). "Consistent with the delay of tumor progression, the high-fat diet enhanced CD4+ and CD8+ T cells in the immune microenvironment at day 8 post-inoculation compared to those in the normal chow diet condition." (PMID 41614948, 2026).
tumor (continued). "Depleting CD4+ T cells, or blocking lymphocyte egress from the lymph nodes, rescues tumor growth in mice with conditional deletion of Dnmt1 in ECs (Dnmt1iECKO) and dramatically shortens overall survival, whereas NK cells are dispensable." (PMID 42156591, 2026). "For instance, during acute SARS-CoV-2 infection, a surge of IL-6 has been recently shown to awaken dormant tumor cells and drive cancer progression, a process facilitated by suppressive CD4+ T cells within the tumor microenvironment." (PMID 41315764, 2026). "RNA microarray analysis showed that CD4 T cells can significantly reduce the progress and proliferation of tumor cell cycle." (PMID 41560039, 2026). "Tumor cells killed by NK cell-mediated ADCC serve as a source of TAAs that are presented by APCs to support the stimulation of CD4 + Th1 cells, thereby maintaining high levels of miR-19a-3p." (PMID 41582199, 2026). "The TGF‐B1/TGFBR2 signalling axis mediated tumour‐CD4+ T cell communication, suppressing CD4+ T cell anti‐tumour activity and resulting in reduced CD4+ T cell enrichment and poor prognosis." (PMID 41492119, 2026). "NK cell-mediated ADCC (perforin/granzyme-induced apoptosis) can increase tumor cell membrane permeability by forming pores and trigger CD4 + Th1-mediated antitumor immunity." (PMID 41582199, 2026). "In a murine intrahepatic tumor model, KCTD1 knockdown synergizes with anti-PD-1 therapy, resulting in enhanced tumor infiltration by CD4+ and CD8+ T lymphocytes and improved anti-tumor efficacy." (PMID 41765960, 2026). "In colorectal cancer, ICOS was mainly expressed by CD8+ and CD4+ T‐cells; thus a higher percentage of ICOS+ T‐cells in the peripheral blood and tumor was associated with improved prognosis." (PMID 41474629, 2026). "We further found that potent anti-tumor immunity was associated with increased tumor-infiltration of CD8+ T cells and positively correlated with tumor-infiltrating CD8+ to CD4+ T cell ratios." (PMID 42256206, 2026). "In comparison to non-transduced CD7N cells and Bulk CAR-T cells, scRNA-seq analysis of CD7N CAR-T cells revealed a unique AQP3+ CD4+ T-cell subset following exposure to tumor cells." (PMID 41742839, 2026). "This combination boosts the presence of CD4+ and CD8+ tumor-infiltrating lymphocytes, reprograms tumor-associated macrophages toward an M1-like phenotype, and improves tumor control and metastasis reduction." (PMID 41763215, 2026). "At the same time, to further enhance tumor antigen presentation and recruit more CD4+/CD8+ T cells, PEG@AuCZ@CC NPs efficiently promoted ICD by inducing a multiple‐death strategy (ferroptosis and cuproptosis)." (PMID 41090529, 2026). "Our study revealed that HBV core protein HBx suppressed miR‐19a‐3p, a critical regulator restoring CD4+ T cell anti‐tumour activity in the DLBCL microenvironment." (PMID 41492119, 2026). "CD4+ helper T-cells, particularly T helper type 1 (Th1) polarized populations, augment tumor-restraining responses by producing IFN-γ and IL-2, and by supporting cytotoxic priming." (PMID 41562715, 2026). "Among mice reconstituted with CD4+ T cells, the HBx‐overexpressing tumours showed increased growth kinetics and final weights, which were accompanied by reduced intratumoural CD4+ T cell infiltration and decreased IFN‐γ and Granzyme B levels." (PMID 41492119, 2026). "Then, the miR‐19a‐3p agomir treatment restored CD4+ T cell infiltration and effector molecule production, along with reduced tumour growth in HBx‐overexpressing xenografts." (PMID 41492119, 2026). "In the GOYA cohort, high expression of BAMBI correlated with diminished CD4+ T cell enrichment in tumour tissues, a trend mirrored by TGFB1." (PMID 41492119, 2026). "In vivo, RRx-001 significantly suppressed tumor growth (p < 0.001), reduced tumor weight, enhanced infiltration of CD4+ and CD8+T cells, increased M1 macrophage polarization, and downregulated PD-L1 expression." (PMID 41888099, 2026).
tumor (continued). "The mRNA Nb-LNP neoantigen vaccines also induced substantially higher levels of DC maturation and more potent antigen-specific T cell responses, in particular CD4+ T cell responses, which are critical for initiation of anti-tumor immunity and immune memory." (PMID 41893776, 2026). "Tumours established without CD4+ T cell transfer exhibited accelerated growth and higher tumour burden compared with those receiving CD4+ T cells." (PMID 41492119, 2026). "Not only does this activate the direct killing function of NK cells, but it also recruits CD8+ T cells, CD4+ T cells, and NK cells to co-infiltrate tumor tissues by modulating chemokine secretion in the tumor microenvironment (TME)." (PMID 41516373, 2026). "This association between the status of systemic CD4+ T cells and survival is consistent with the requirement of a functional CD4+ T cell response for the development of effective anti-tumour immunity." (PMID 41574275, 2026). "In summary, this study revealed that HBV infection suppresses miR‐19a‐3p in DLBCL, subsequently activating the Wnt‐TGF‐β signalling and compromising CD4+ T cell‐mediated anti‐tumour immunity through ligand–receptor crosstalk." (PMID 41492119, 2026). "Single-cell analysis of tumor-infiltrating lymphocytes revealed that this combination therapy uniquely expanded tumor-reactive memory-phenotype CD4 and CD8 T cells." (PMID 41904478, 2026). "Tumor cells subvert immunity by suppressing IFN-γ in CD4+ T cells via Wnt signaling while promoting IL-17a production, thereby impairing antitumor surveillance." (PMID 41515289, 2026). "Increased CD4+ and CD8+ and decreased tumor-associated macrophage infiltration in post-treatment tumors are noted." (PMID 41585138, 2026). "Functionally, SATB1 KO reduces suppressive capacities of human Treg cells but boosts tumor clearance via CD4 CAR T cells in a preclinical, humanized mouse model." (PMID 42286212, 2026). "As tumours are infiltrated by different T cells subsets including regulatory CD4+ T cells (Tregs) and memory CD8+ T cells, we first compared the phenotype of T cell populations in paired blood and MPE samples." (PMID 41574275, 2026). "Using our mouse model designed to delete DNA-PKcs expression in mature CD4+ or CD8+ T cells, we show that loss of DNA-PKcs results in T cells that are unable to control tumor growth or induce allogeneic graft rejection." (PMID 41505255, 2026). "The majority of CD4+ tumor-infiltrating T cells exhibited an EM phenotype, with one exception showing a higher number of naive CD4+ T cells in mice treated with Fc-WT-IL7." (PMID 41542752, 2026). "Mechanistically, HBx‐mediated down‐regulation of miR‐19a‐3p activated the BAMBI/Wnt signalling pathway, thereby enhancing TGF‐β1 secretion and suppressing the anti‐tumour activity of CD4+ T cells." (PMID 41492119, 2026). "Spleen regeneration stimulated early occupancy of the tumor niche by macrophages, as well as influx of CD4+ T‐lymphocytes and B‐lymphocytes into the tumor, while infiltration of CD8+ T‐lymphocytes was suppressed." (PMID 41522488, 2026). "Consistent results were obtained in CT-26 allografts, where Nat10 KO increased the accumulation and activity of CD8+ and CD4+ T cells, which were correlated with tumor growth suppression." (PMID 41542770, 2026). "Specifically, the PTPN family appears to inhibit CD4+ T cell activity, which contributes to immune evasion by the tumor." (PMID 40570022, 2025). "CD4+ T cell subsets, particularly Th2 and Th17, contribute to tumor progression by promoting TAM and MDSC recruitment via IL-4, IL-13, and IL-17-driven pathways." (PMID 40475782, 2025). "T cells in the tumor cells (CD4+ FOXP3+ CD25+ T cells and CD8+ FOXP3+ CD25+ T cells) are immunosuppressive due to their increased secretion of inhibitory cytokines and inhibition of naïve T cell proliferation." (PMID 40563393, 2025).
tumor (continued). "Our findings indicate that the expression of mitochondrial MYO19 and DNA2 is significantly associated with the tumor infiltration of various immune cells, including B cells, T cells (CD8+ and CD4+), neutrophils, macrophages, and dendritic cells." (PMID 40839681, 2025). "These present antigens via MHC molecules, triggering cytotoxic CD8 + T cells to lyse tumour cells and helper CD4 + T cells to enhance immune responses." (PMID 40624498, 2025). "In the early phase (3–5 days post-ablation), immune activation likely reflected responses to novel and known tumor antigens, with reactivated memory B-cell and clonal expansion of activated CD4+ T-cells." (PMID 41228287, 2025). "Taken together, our data suggest that CD8+ T cells alter the homing of CD4+Foxp3+ T cells into the tumor microenvironment." (PMID 40553564, 2025). "Tumor-infiltrating immune cells, particularly CD8+ cytotoxic T lymphocytes, CD4+ helper T cells, and NK cells, are associated with favorable prognosis in CRC." (PMID 41244711, 2025). "This study provides a robust framework for discovering tumor-specific CD4+ TCRs and highlights their critical role in antitumor immunity." (PMID 40634636, 2025). "Spatial relationships between polymorphonuclear myeloid-derived suppressor cells and multiple other cell types in the tumor microenvironment (including tumor cells, CD4+, and CD8+ T cells) were enriched in tumors with FGFR2 alterations." (PMID 39969434, 2025). "CD4+ T-cells are also among the principal cells and coordinators of innate immune responses, and research that they play a role as effective anti-tumour cells." (PMID 40061872, 2025). "In doing so, we reveal the previously unappreciated ability of the senescence program to engage tumor-immune equilibrium and highlight the importance of CD4 T cells in antitumor immunity potentiated by RAS inhibition." (PMID 40299790, 2025). "CD4+ Th2 cells are necessary to establish tumor protection in response to TSLP in the skin, and this protective effect persists in the absence of CD8+ T or B cells." (PMID 39744942, 2025). "Flow cytometry revealed 32.7% DC maturation efficiency and increased tumor-infiltrating CD8+/CD4+ T cell populations, confirming systemic immune activation." (PMID 40892295, 2025). "Specifically, CD3+CD4+ splenocytes from aged OVX 4T1 tumor-bearing mice treated with calcitriol showed increased Stat5a and Vdr mRNA expression." (PMID 40894304, 2025). "Overall, CD4 T cell-mediated trogocytosis contributes to immunosuppression in the tumor microenvironment." (PMID 39741180, 2025). "Future experiments will reveal immune regulation or possibly direct anti-viral functions of these LANA-specific CD4+ T cells in the PEL tumor microenvironment." (PMID 41350288, 2025). "More importantly, the frequencies of ICOS+CD4+ T cells in the blood correlated with the serum SP-D levels in injured lungs 15 days after tumor inoculation." (PMID 40198121, 2025). "Remarkably, a subset of MIF−/− mice exhibited complete tumor rejection with a significant decrease in Tregs and an increase in CD4+ and CD8+ lymphocytes." (PMID 41159021, 2025). "Tumor microenvironments rich in NETs were found to be populated by CD4 and CD8 T-cells that were metabolically and functionally exhausted." (PMID 40236693, 2025). "Intriguingly, blocking either CD4+ or CD8+ T cells impaired the tumor control mediated by CR108 + OVA." (PMID 40606756, 2025). "These CD4+ T cells showed tumor-suppressing effect on CRC growth in mice with humanized immune system by recognizing human leukocyte antigen class II (HLA-II) on tumors." (PMID 40248695, 2025). "CD8+ T lymphocytes are known for their cytotoxic effects against tumor cells, whereas CD4+ T lymphocytes are recognized for their robust anti-tumor immune responses." (PMID 40574736, 2025). "In studies, deleting c-Rel during the first five days after tumor implantation reduced CD4 T cell priming, resulting in more naive T cells but impaired effector functions." (PMID 40370445, 2025).
tumor (continued). "CD4+ T-cells play a dual role in cancer immunology, acting as both tumor-promoting and tumor-suppressing agents depending on their differentiation, cytokine profiles, and interactions with other immune components." (PMID 40860882, 2025). "Tumours also attract regulatory T cells (Treg), which are suppressive of CD4+ and CD8+ cells, allowing for survival in the TME." (PMID 40943226, 2025). "We observed that the numbers of Tbet+ICOS+ Th1-like CD4+ T cells in tumors correlated to reduced frequencies of CD45−CD31high tumor endothelial cells and increased frequencies of MECA-79+ TA-HECs after anti-CTLA-4 treatment." (PMID 40460830, 2025). "TAGAP overexpression in CD4+ T cells also inhibited LUSC tumor growth and boosted immune infiltration in vivo." (PMID 39998561, 2025). "In general, tumor-associated macrophages (TAMs) facilitate the proliferation and spread of tumors, whereas CD8+ cytotoxic T cells and CD4+ Th1 cells provide support for the immune response against tumors." (PMID 41169398, 2025). "IHC analysis was performed on the tissue sections for identification of T-helper (CD4) and cytotoxic T lymphocytes (CD8), and of tumor-associated (CD68; resident macrophage) and M1-polarized macrophages (L1/MAC387)." (PMID 40146757, 2025). "Increasing histology-driven evidence from mouse and human tumor tissues highlights the spatial location of specific CD4+ subsets within the TME and their proximity to other immune cells as critical biomarkers for determining ICI efficacy." (PMID 40561008, 2025). "Optimizing vaccine design (antigen and adjuvant selection), concentrating on the role of CD4 + T cells in tumor vaccines, and utilizing combination immunotherapy will be new keys to increasing the efficacy of GBM vaccines." (PMID 40756669, 2025). "IL-6 inhibition further promotes CD8+ T cell-dependent tumor elimination through the restoration of CD4+ T cell function in an IFN-γ-dependent manner." (PMID 41294748, 2025). "LAG-3 is highly co-expressed with PD-1 in tumor-infiltrating CD4+ and CD8+ T lymphocytes, and dual inhibition of LAG-3 and PD-1 has demonstrated synergistic antitumor activity in preclinical studies." (PMID 39751894, 2025). "Effective neoantigens presented by the MHC can activate CD8+ and CD4+ T cells, triggering tumor-specific immune responses." (PMID 41312385, 2025). "The ligand IL16 was highly expressed specifically in IBC tumour B and T cells, whereas its receptor (CD4) was expressed mainly in myeloid cells." (PMID 40624675, 2025). "In mouse models of spontaneous tumor development, interfering with IL-1β+ CD4+ T cells or IL-1R1+ neutrophils interrupted communication, reduced neutrophil ferroptosis, boosted antitumor immunity, and countered chemoresistance." (PMID 40732268, 2025). "Tregs can produce the immunosuppressive cytokines IL-10 and TGF-β to deplete IL-2, constituting the CD3+CD4+ subpopulation to suppress the activity of effector T cells and effective anti-tumor immune response." (PMID 40703522, 2025). "As a result, this impairs the activation of antigen-specific cytotoxic T lymphocyte (CTL) responses and hinders the differentiation of CD4+ T cells into anti-inflammatory Th1 cells, ultimately facilitating promoting tumor progression 38-39." (PMID 40303336, 2025). "CD1C+ dendritic cells are thought to induce the CD4+ helper T cell response for tumor antigen presentation." (PMID 41279473, 2025). "In active OpdA-treated tumor-bearing mice, there was a significant increase in the percentages of tumor-specific CD4+/IFN-γ+ and CD4+/IL-10+ T lymphocytes in the spleen." (PMID 41019059, 2025). "Differentiated CD4+ T cells then migrate to tumor tissues or adjacent lymphoid tissues to participate in tumor immune responses." (PMID 40176817, 2025). "The high-risk group showed elevated Treg cell expression and lower levels of CD8+/CD4+ T cells, critical for tumor immunity." (PMID 40109870, 2025).